ANXA1 (annexin A1)
Diseases named in the same sentence as ANXA1 in open-access papers (continued):
Sharing a sentence is not in itself a finding about the gene and the disease.
psoriatic arthritis (1 paper, 2014). Joint inflammation associated with psoriasis. "The role of ANXA1 in the pathogenesis of psoriatic arthritis is unclear, and further study is necessary." (PMID 25010044, 2014). "Also the serum STIP1 or moesin, CK17, ANXA1 level was not correlated with DAS28 or BASDAI in patients with psoriatic arthritis." (PMID 25010044, 2014).
relapsing-remitting MS (1 paper, 2023). "Intriguingly, the same cysteine residue on annexin A1, Cys189, has been shown to be modified by DMF in neurons and astrocytes, and low annexin A1 levels were found to correlate with severity of relapsing-remitting MS, a disease for which DMF is used as treatment." (PMID 37578391, 2023).
retinal degeneration (1 paper, 2026). Degeneration of the retina. "In PD, retinal degeneration mirrors brain pathology, and reduced AnxA1 activity may impair the resolution of inflammation." (PMID 41639875, 2026). "Overall, it is possible that coordinated AnxA1/AnxA2 activity may mitigate retinal damage, improve the removal of toxic aggregates, and preserve vision, highlighting annexin pathways as promising therapeutic targets for retinal degeneration in PD and AD." (PMID 41639875, 2026).
retinal vein occlusion (1 paper, 2023). An occlusion of the retinal vein. "Proteins that were upregulated in our study and in experimental retinal vein occlusion included fibronectin, annexin A1, galectin-3, alpha-crystallin B chain, vimentin, annexin A2, STAT1, GFAP, osteopontin, vitronectin, and clusterin." (PMID 37175625, 2023).
rheumatic diseases (1 paper, 2020). "Therefore, low density lipoprotein related protein 1 (LPR-1), thrombospondin-1 (TSP-1), voltage dependent anion channel 2 (VDAC2) and annexin A1 were chosen as proteins of special interest, based on literature data supporting their involvement in arthritic and rheumatic diseases." (PMID 32586320, 2020).
salivary gland tumors (1 paper, 2024). "Some of the identified peptides were derived from proteins previously suggested as potential biomarkers of salivary gland tumors (ANXA1, BPIFA2, FGB, GAPDH, HSPB1, IGHG1, VIM) or tumors of other tissues or organs (SERPINA1, APOA2, CSTB, GSTP1, S100A8, S100A9, TPI1)." (PMID 39201484, 2024).
sarcoma (1 paper, 2023). A usually aggressive malignant neoplasm of the soft tissue or bone. "To further investigate the correlation between the expression levels of ANXA1 and TILs, we explored the correlation between the expression levels of ANXA1 and the infiltrating abundance of TILs in sarcoma patients through the TIMER database." (PMID 36988561, 2023). "In sarcoma, the expression levels of ANXA1 were positively correlated with those of MMP9 (r=0.204, P=9.43e-04), COL1A2 (r=0.349, p=8.87e-09), S100A4 (r=0.574, P<0.001), VIM (r=0.48, P<0.001) and S100A11 (r=0.638, P<0.001)." (PMID 36988561, 2023).
severe combined immunodeficiency (1 paper, 2016). Severe combined immunodeficiency (SCID) comprises a group of rare monogenic primary immunodeficiency disorders characterized by a lack of functional peripheral T lymphocytes resulting in early-onset severe respiratory infections and failure to thrive. "Finally, orthotopic xenografts obtained by engrafting WT, PGS and ANXA1 KO MIA PaCa-2 cells in the pancreas of SCID (Severe Combined Immunodeficiency) mice showed that the absence of intracellular ANXA1 did not affected the tumour mass but strongly decreased the metastatization process." (PMID 27412958, 2016).
Shock (1 paper, 2016). The state in which profound and widespread reduction of effective tissue perfusion leads first to reversible, and then if prolonged, to irreversible cellular injury. "LPS-induced endotoxic shock in ANXA1–/– mice was also correlated with increase in TNFα, IL-1 and IL-6 levels in the blood when compared with wild-type mice." (PMID 27540524, 2016).
Simpson-Golabi-Behmel syndrome (1 paper, 2019). Simpson-Golabi-Behmel syndrome is a rare X-linked multiple congenital anomalies syndrome, characterized by pre- and postnatal overgrowth, distinctive craniofacial features, variable congenital malformations, organomegaly and an increased tumor risk. "Simpson Golabi Behmel syndrome is associated with glypican-3 loss-of-function mutations, implicating a possible link between adipocyte AnxA1 expression and this poorly characterized cell surface proteoglycan." (PMID 31337068, 2019). "In contrast, in mature adipocytes from patients with Simpson Golabi Behmel syndrome, an overgrowth disorder leading to craniofacial, skeletal, cardiac, and renal abnormalities, AnxA1 mRNA and protein amounts were approximately 65-fold higher compared to their corresponding preadipocytes." (PMID 31337068, 2019).
spondyloarthritis (1 paper, 2020). "Recent proteomic analysis of SF from RA patients and spondyloarthritis (SpA) patients identified elevated levels of many neutrophil proteins in RA SF, including MPO, cathepsin G, annexin-A1 and NGAL." (PMID 33469455, 2020).
Thrombocytopenia (1 paper, 2022). A reduction in the number of circulating thrombocytes. "The AnxA1 mimetic significantly reduced thrombocytopenia and haemoconcentration in response to DENV infection and displayed efficacy on controlling innate immunity mediators, with more significant effects in spleen values rather than plasma levels for CCL5 and IL-6." (PMID 35293862, 2022).
thyroid tumor (1 paper, 2022). A benign or malignant neoplasm affecting the thyroid gland. "Besides, in addition to being the most prominent candidate according to the IHC staining and PRM-MS quantification results, ANXA1 has previously been reported in thyroid tumors." (PMID 35923625, 2022). "In addition, ANXA1 is a promising biomarker for differentiating FvPTC from the other thyroid tumors." (PMID 35923625, 2022).
Tremor (1 paper, 2024). An unintentional, oscillating to-and-fro muscle movement about a joint axis. "We then performed spectral analysis on mice depleted of Anxa1+ SNc dopaminergic neurons and found a slight shift in the frequency of tremor, resembling the phenotype of MitoPark mice at 16 weeks." (PMID 39763754, 2024). "Further, we found that the inhibition of transmitter release in Anxa1+ neurons led to bradykinesia and tremor." (PMID 39763754, 2024). "Finally, although targeted manipulation of Anxa1+ neurons led to significant bradykinesia and tremor reminiscent of the early stages of disease in MitoPark mice, it did not affect immobile time or akinesia." (PMID 39763754, 2024). "Furthermore, specific ablation and silencing of SNc DANs and the Anxa1+ subtype revealed their important role in this tremor phenotype." (PMID 39763754, 2024).
vascular tumor (1 paper, 2020). "Studies of additional tumor indications and correlating rodent translational models will be useful for further assessment of anxA1 as a vascular tumor target." (PMID 32497150, 2020). "Our results demonstrate that vascular anxA1 expression is present in a subset of human lung tumors and rodent tumor models, thus supporting its potential as a vascular tumor target for biologic agents." (PMID 32497150, 2020).
xanthoma (1 paper, 2015). A non-neoplastic disorder characterized by a localized collection of histiocytes containing lipid. "Interestingly, our in vivo results show that although hr-anxA1 treatment did not affect intimal xanthoma and small lesion formation it afforded substantial inhibitory effects on progression of small lesions towards advanced lesions." (PMID 26090792, 2015).
ZIKV infection (1 paper, 2023). "Like the DENV study, Molás and colleagues have demonstrated a correlation between reduced levels of AnxA1 in placental tissue and increased inflammation in pregnant women with ZIKV infection, suggesting that AnxA1 may play a role in the severity of ZIKV-associated complications." (PMID 37190040, 2023).
Zinc deficiency (1 paper, 2019). A deficiency of the essential metal Zinc; an essential cofactor for many enzymes. "In addition, therapeutic drug prediction indicated that CXCR2 and ANXA1 may be targets of drugs, suggesting these two genes may be implicated as therapeutic targets to reduce risk of zinc deficiency." (PMID 30770772, 2019). "Therefore, CXCR2, ANXA1, and CCR3 would be potential biomarkers for zinc deficiency in mice." (PMID 30770772, 2019).
tumor (352 papers, 2005 to 2026). "ANXA1 has also been implicated in tumor metabolism, including lipid metabolism and cholesterol metabolism, by modulating metabolic enzyme activity and influencing the progression of both malignant and benign diseases." (PMID 40390008, 2025). "It shows that ANXA1-high tumors harbor significantly more B-cells, cancer-associated fibroblasts (CAFs), tumor-associated macrophages (TAMs), and natural killer (NK) cells compared to ANXA1-low tumors." (PMID 40361334, 2025). "These processes are strongly associated with tumor aggressiveness, making them important parameters when investigating the impact of ANXA1." (PMID 40361334, 2025). "ANXA1, known for its immunomodulatory properties, has emerged as a significant molecule potentially influencing tumor and metastasis progression, along with an association with an immunosuppressive microenvironment." (PMID 40361334, 2025). "Through loss-of-function experiments, we established that ANXA1 acts as a tumor suppressor in OSCCs, particularly in CAL27 cells with a stem cell phenotype, because its downmodulation restored the motility and resulted in a more aggressive phenotype." (PMID 40227604, 2025). "NRF2 upregulated ANXA1, which promoted tumor‐associated macrophage (TAM) recruitment and M2 polarization." (PMID 40583858, 2025). "Nevertheless, ANXA1 is also implicated in promoting tumor immune tolerance, and the PD-1/PD-L1 axis is the most well-characterized immune checkpoint." (PMID 40361334, 2025). "Taken together, these complementary dynamic analyses support a role for ANXA1 in promoting dynamic tumor cell association with blood vessels." (PMID 40683881, 2025). "A strong association between high ANXA1 expression and a poorly differentiated tumor grade was detected and associated with decreased survival rates." (PMID 41283264, 2025). "ANXA1 has been implicated in vascular endothelial cell sprouting, and ANXA1 inactivation has been shown to impair angiogenesis, tumor growth and metastasis in mouse models." (PMID 38659028, 2024). "The deregulation of ANXA1 is frequently associated with cancer development, contributing to tumor initiation, proliferation, and metastasis." (PMID 38893148, 2024). "Some studies directly link the reduction or loss of ANXA1 in HSCC to tumor development and other HNSCC-related oncogenes such as EGFR and miR-196a/b." (PMID 38893148, 2024). "ANXA1 has recently been recognized as a valuable diagnostic or prognostic biomarker, and is often differentially expressed in tumor and normal tissue samples." (PMID 38102661, 2023). "Accumulated evidences indicate that the ubiquitous 37-kDa ANXA1 protein dysregulation is associated with tumor development, progression, and invasion in different cancer types." (PMID 36745330, 2023). "The angiogenic function of Tppp3+ monocyte is mainly supported by high expression of Anxa1 and Anxa2, encoding proteins involved in tumor angiogenesis and metastasis." (PMID 37483625, 2023). "An increased Th2 lineage commitment was observed in annexin A1-deficient T cells in a mouse model of allergic inflammation, which is inconsistent with our findings and warrants further validation in tumor models." (PMID 37056569, 2023). "ANXA1 overexpression is linked to increased tumor hypoxia, a characteristic of tumors often replicated in 3D multicellular spheroid cultures, mimicking in vivo conditions." (PMID 37884554, 2023). "Comparisons between healthy and tumor endothelium have shown that tumor-associated endothelial caveolae selectively recruit Annexin A1, thereby allowing for targeted uptake of conjugated antibodies into tumors but not normal parenchymal tissue." (PMID 35431977, 2022). "Simultaneously, our systematic investigation identified a possible underlying mechanism by which tumour immune evasion is regulated by ANXA1 through activating the NF‐kB/IL‐8/DC pathway." (PMID 35770335, 2022).
tumor (continued). "In fact, the contrasting patterns of ANXA1 expression in different tumor types is just one of the enigmas in deciphering the underlying regulatory mechanisms and phenotypic specificity of ANXA1." (PMID 36247003, 2022). "A study has shown the association of ANXA1 with progression and metastasis of cancer, suggesting its role in regulating tumor cell proliferation." (PMID 36035163, 2022). "Considering the role of IL‐8 in DC maturation, our study verified ANXA1 influence on IL‐8 expression to determine the precise regulatory mechanism of ANXA1 underlying the tumour‐immune system in GBM." (PMID 35770335, 2022). "The importance of this DAMP in tumor immunology can be noted by the fact that the low expression of ANXA1 is often associated with poor DCs and T lymphocyte infiltration in the tumor bed and a higher ability of different human cancers to escape immunity." (PMID 36015189, 2022). "Another RBP, ANXA1, which promotes the progression of BC by facilitating the Treg cell-mediated anti-tumor immunity, is associated with the poor survival of BC patients and a higher risk of breast malignancy." (PMID 35205391, 2022). "ANXA1 deficiency suppresses tumor growth by altering the gut microbiome, regulating serum metabolite levels, and interacting with hub genes." (PMID 35664067, 2022). "Orthotopic implantation of the Annexin-A1-deficient cells produced dormant viable microscopic tumor foci that eventually attained proliferative capacity leading to the formation of tumors with a predominantly sarcomatoid histology." (PMID 33800279, 2021). "The results showed that CCIs of epithelial tumor cells, cancer-associated fibroblasts, and tumor-associated macrophages through integrin-related and ANXA1–FPR pairs were poor-prognostic CCIs and are potential therapeutic targets." (PMID 34522794, 2021). "ANXA1-high PC was significantly associated with a high fraction of fibroblasts and keratinocytes in the tumor microenvironment." (PMID 33804148, 2021). "More importantly, we discovered the high level of ANXA1 was closely linked to the tumor size of PTC samples and predicted unfavorable prognosis of patients, emphasizing the important clinical significance of ANXA1 in PTC patients." (PMID 33531975, 2021). "Future studies should further examine mechanisms underlying Anxa1 upregulation in tumor tissue after BNCT." (PMID 33446132, 2021). "ANXA1 high PC was significantly associated with a high fraction of fibroblasts and keratinocytes in the tumor microenvironment (TME)." (PMID 33804148, 2021). "Extracellular or membrane-associated, externally facing Annexin A1 synthesized by cancer cells has many possible functions in the tumor microenvironment." (PMID 33800279, 2021). "Herein, patients with higher ARID1A and ANXA1 expressing tumours showed increased recurrence risk and a higher risk of dying from this disease." (PMID 33276477, 2020). "The N-terminal domain confers many of the functional properties of anxA1 and is highly susceptible to proteolytic cleavage in a number of physiological contexts, including tumor endothelium." (PMID 32497150, 2020). "We further found that ANXA1 protein was associated with tumor invasiveness in 35 Japanese TNBC patients." (PMID 31461932, 2019). "As annexin A1 (ANXA1) is implicated in the establishment of tumour metastasis, the role of the protein in PC progression as a component of extracellular vesicles (EVs) has been investigated." (PMID 30518142, 2018). "The repertoire of proteins that were modulated in normal breast epithelial cells and tumor cells in response to ANXA1 deficiency was distinct." (PMID 29233185, 2017). "In this report, we show an underlying mechanism that demonstrates that macrophage ANXA1 is required for and plays an important role in the tumour microenvironment, and is important in the induction of expression of M2 macrophage subset markers." (PMID 29263330, 2017).